RN7SL299P (RNA, 7SL, cytoplasmic 299, pseudogene)
Gene: Miscellaneous RNA gene on chromosome 1 (232,222,866 to 232,223,145, forward strand). Ensembl gene ENSG00000242794.
Homologues: Orthologues: chimpanzee Metazoa_SRP (100% identical), macaque Metazoa_SRP (90% identical). Paralogues in human: RN7SL1 (82% identical), RN7SL3 (82% identical), RN7SL2 (82% identical), RN7SL786P (81% identical), RN7SL220P (81% identical), RN7SL769P (80% identical), RN7SL408P (80% identical), RN7SL44P (80% identical), RN7SL607P (80% identical), RN7SL218P (79% identical), RN7SL333P (79% identical), RN7SL357P (79% identical), and 704 more.